TNF (tumor necrosis factor)
Diseases named in the same sentence as TNF in open-access papers (continued):
Sharing a sentence is not in itself a finding about the gene and the disease.
infection (continued). "However, Pellino2-decificient BMDCs secreted reduced levels of IFN-β and IL-12p70 in response to infection by S. aureus relative to WT cells, whereas expression levels of TNF-α levels were not affected." (PMID 34588221, 2021). "In conclusion, this study indicates that at the initial stage of SARS-CoV-2 and SFTS infection, the blood indices of patients are distinct from each other, including WBC count, absolute LYMPH count, PLT count, absolute CD4+ T cells count, and IL-6, TNF-α, D-D, CRP and FIB levels." (PMID 34238962, 2021). "As the activation of immune pathways like NF-κB or TNF leads to upregulation of adhesion molecules (e.g., ICAM-1 and VCAM-1) and recruitment of leukocytes at the site of infection, this may ultimately help Borrelia to adhere to endothelial cells and cross the BBB." (PMID 34819924, 2021). "The cytokines IL-6, IL1-ß, and TNF-α were the highest in the L. majorWT group and surprisingly not recapitulated in the L. majorR group; IL-6 in C57BL/6 mice was reported to be responsible for Th2 responses but not required to control the disease since IL-6 KO mice were able to control infection." (PMID 34972189, 2021). "Besides, the infection resulted in decreased production of IL-12 and TNF, but not IL-6, at 24 h and 48 h." (PMID 34354963, 2021). "After vaccination with H1-DDA/TDB, both IFN-γ+TNF+IL-2+ triple-positive and IFN-γ−TNF+IL-2+ double-positive multifunctional T cells can be detected > 1 year post-vaccination in spleens and peripheral blood and accumulate in the lungs of vaccinated mice after infection with Mtb." (PMID 34351501, 2021). "Moreover, the plasma levels of IL-2, IL-6, IL-8, IL-10, and TNF-α, observed in severe infection, are prominently greater than those with nonsevere infection." (PMID 34844296, 2021). "Interestingly, expression of pro-inflammatory IL-1 was modestly down-regulated in all cell types after infection, whereas IL-10 and TNFα expressions were not significantly regulated by infection in this system." (PMID 33730024, 2021). "The expression levels of TNF-α [NM_013693] and COX2 [NM_011198] mRNA were significantly upregulated in the skin of WT mice, but not in that of RAGE-/- mice following infection with venestatin-knockdown larvae, compared with those infected with control larvae (TNF-α, p < 0.01; COX2, p < 0.0001)." (PMID 34081755, 2021). "Our results showed that HTNV infection led to elevated cytokine production, including CXCL-1, CCL-5, IL-6, IL-12, TNF-α, and IFN-γ in Nlrc3−/− mice, and the levels of these cytokines peaked at 6 or 9 dpi; in comparison, WT mice had weaker cytokine responses throughout the infection process." (PMID 34335602, 2021). "In addition, UPEC-mediated TNF release occurs 2 h after infection in in vivo models of UTIs but not in in vitro models." (PMID 34835359, 2021). "Furthermore, infection of ECSIT+/+ and WT BMDMs with S. typhimurium showed comparable activation of NF-κB and MAPK pathways and induction of IL-6 and TNF-α." (PMID 34032637, 2021). "Unlike Mycopar, the early induction at 2 MPV of IFN-γ, IL-1α, TNF-α, IL-17 and CXCL9 in pgsN and pgsNQ groups may help in controlling early infection with M. paratuberculosis and provide more protection against associated pathological lesions as was clearly shown in liver." (PMID 32957508, 2020). "Deficient adaptive immunity in the periphery is likely influencing the NP response to infection, as several inflammatory cytokines and chemokines were higher at onset and/or sustained longer in sOP children during AOM pathogenesis, including CCL2, IL-12, IL-17A, and TNF-a." (PMID 32595639, 2020). "Moreover, we demonstrated that while IFNAR signaling does not affect the amount of TNF-α produced by BMMCs in response to rVSVΔM51 at 16 h post-infection, IL-6 generation was higher in IFNAR-intact BMMCs compared to IFNAR-blocked and IFNAR−/− BMMCs." (PMID 33261178, 2020). "However, protected mice in our experiments did not exhibit higher TNF-α levels after challenge infection." (PMID 32411624, 2020).
infection (continued). "Moreover, mice that produced low antibody levels were not able to control infection, therefore progressed to disease; providing direct evidence for the TNF gene-regulating humoral immunity during central nervous system (CNS) M. tuberculosis infection." (PMID 32742607, 2020). "Here we observed that elevated cytokines during Brucella infection in BS-treated mice including IL-12, TNF, IFN-γ, and IL-1β are important mediators of immune responses to intracellular pathogens, while MCP-1 also plays a central role in the maintenance of inflammation aimed to limit the infection." (PMID 31893609, 2020). "To test whether ∆M36 infection would collaborate with TNF to induce the death of non-myeloid cells, we treated apoptosis-resistant endothelial cells with TNF, IFNβ, or IFNγ starting 1 hpi." (PMID 33126536, 2020). "BMDM produced but SVEC4-10 cells did not produce TNF during infection." (PMID 33126536, 2020). "TNF-α was not affected by infection (F1, 12 = 3.4, P = 0.8) or any first-order interactions, microbiota treatment × V. anguillarum exposure (F1, 12 = 0.1, P = 0.78), microbiota treatment × population (F1, 14 = 2.1, P = 0.17), and population × V. anguillarum exposure (F1, 12 < 0.1, P = 0.92)." (PMID 32970813, 2020). "Moreover, the plasma levels of IL-2, IL-6, IL-8, IL-10, and TNF-α, observed in severe infection, are prominently greater than those in nonsevere infection." (PMID 32299202, 2020). "Loading of BMDM with Lb photo-inactivated by both Strategy #1 (orange bar) and Strategy #2 (red bar) significantly up-regulated IL-6 over their controls, i.e. no treatment (light gray) and infection with live Lb (dark gray and black bar), as true for TNF via Strategy #2." (PMID 33051524, 2020). "However, the anti-inflammatory factor IL-10 expression was observably up-regulated (P < 0.01),while the expression of TNF-α was not significantly different between the two groups after infection with APEC." (PMID 33134350, 2020). "Infection with B. pertussis naturally induces a significant Th1-type T-lymphocyte cytokine response in mice that is characterized by high levels of IL-2, IFN-γ, and TNF-α, a type of immune response that is characteristic of infection by intracellular pathogens." (PMID 33178148, 2020). "In addition, our study showed that infection with L. infantum did not determine a significant difference in the production of TNF-α and IL-6." (PMID 31961876, 2020). "Noticeably, suppression of cytokine expression (IFN and TNF-α) was compromised in NS1031 RG-AIV at an early stage of infection (6 hpi), which is consistent with its defective inhibition of PKR activation, a factor potentially responsible for its poor infection outcomes." (PMID 32226416, 2020). "Moreover, infection of human moDCs with H. pylori rapidly induces SOCS3 expression, which requires the type IV secretion system (T4SS), release of TNFα, and signaling via the MAP kinase p38, but appears to be independent of TLR2, TLR4, MEK1/2 and STAT proteins." (PMID 33023610, 2020). "Furthermore, phagocyte recruitment to the site of infection is accompanied by a macrophage-dependent local upregulation of TNFα when neutrophils are disabled (Rac2-D57N) but not when neutrophils are functional." (PMID 32776983, 2020). "Interestingly, in infected cultures IL-6 and TNFα levels did not increase on day two while for IL-10 the upward trend was maintained at this time point and throughout the three days after infection with MCMV." (PMID 32455939, 2020). "Similarly, in spleens from LCMV-infected RAG1 KO mice, there were no significant changes for TNF, IL-1β and IL-6 mRNAs post infection." (PMID 32310998, 2020). "The increase in the respiratory levels of those inflammatory factors, especially TNF-α, contributes to clearance of the virus during the early stages of RSV infection; however, their continued production exacerbates lung injuries during the late stages of infection." (PMID 32322251, 2020).
infection (continued). "While some cytokines/chemokines such as TNFα and MIP-1β peaked very early after H5N1 infection (12 h), others, i.e. IL-1α and RANTES peaked somewhat later (at 30 h), followed by KC (neutrophil-activating protein-3) and IL-6, reaching their peak at 72 h after infection." (PMID 33362782, 2020). "Importantly, CASP8 plays a central pathogen sensing role that primes cells for apoptosis and collaborates with the TNF-signaling for the execution when vICA is absent during infection." (PMID 33126536, 2020). "The TNF-α levels in non-vaccinated/infected mice were comparable to vaccinated/infected mice at 10 days pi, lowest at 21 days pi and spiked again in response to re-infection." (PMID 33414785, 2020). "In response to HPIAVs infection, such as infection by H5N1, which induces deregulated pro-inflammatory cytokine expression, inhibition of c-Jun, a target molecule of JNK and a component of AP-1, has been shown to suppress the expression of IFNβ and other cytokines, including IL-6 and TNFα." (PMID 32709018, 2020). "In addition, it has been shown that infections by the H9N2 influenza virus strain, which originated from swine hosts, in BALB/c mice resulted in inflammation and injury in the lung with production of pro-inflammatory cytokines including TNFα, IL-1β and IL-6." (PMID 32709018, 2020). "It was also suggested that infection of granulocytes resulted in bystander apoptosis in a non-virus dependent manor via Tumor Necrosis Factor (TNF) superfamily-mediated apoptosis, further hindering the ability of the host immune system to generate an effective response." (PMID 33679690, 2020). "TNFα expression was essentially absent in clodronate-treated infected larvae, correlating with a slight reduction in neutrophil recruitment to the infection site." (PMID 32776983, 2020). "For instance, a higher expression of IL-1β and IL-18 may indicate that the infection is due to a gram + bacteria while IL-6 and TNF would have a higher expression in gram negative infections." (PMID 32655547, 2020). "The KEGG pathway enrichment analysis demonstrated that the top pathways involved in TNF signaling, NOD-like receptor signaling, IL-7 signaling, and cytokine-cytokine receptor signaling pathways were overrepresented in the upregulated genes after 6 h of infection." (PMID 33585271, 2020). "Here we investigate the contribution of DRP1 to the pro-inflammatory cytokine response to lipopolysaccharide (LPS) or infection by the human pathogen, methicillin-resistant Staphylococcus aureus (MRSA), and find that DRP1 plays an unanticipated role in post-transcriptional regulation of TNF-α." (PMID 33520735, 2020). "Finally, we measured plasma levels of TNF-α, IFN-γ, IL-6, and IL-1β cytokines by an ELISA to determine if systemic secretion of cytokines offers an indication of anti-parasite protective immunity after infection and re-infection." (PMID 33414785, 2020). "However, many recent papers report that the use of TNF-α inhibitors in AS patients does not significantly increase serious adverse events, including infection, and is safer previously assumed." (PMID 33021982, 2020). "Since we saw a smaller change in gut microbiota in anti-TNF-α-treated mice following RSV infection, we investigated whether increasing airway TNF-α could alter the gut microbiota in the absence of infection." (PMID 32071269, 2020). "We found that TNF neutralization did not alter infection outcome or kidney function in Ahr-/- mice." (PMID 33021470, 2020). "PrimePCR array analysis of hNS/PCs showed that the mRNA levels of inflammatory cytokine related genes (IL-1A, TNFα, IL28A, IL29, NF-KB2), chemokines (CSF2, CCL3, CCL4, CXCR3),TLRs (TLR3, TLR8), IL-10, and Casp9 were all reduced in the Smaducin-6 treated group following ZIKV-FSS13025 infection." (PMID 32544190, 2020).
infection (continued). "Beyond EGFR, UL138 also enhances levels of tumor necrosis factor-alpha (TNF-α) on the surface of infected cells, but more studies are required to define a role for UL138-mediated modulation of TNF-α in HCMV latency or in modulation of the innate response to infection." (PMID 32630219, 2020). "Thus, during ∆M36 infection, both myeloid and non-myeloid cells die by the collaboration of TNF-dependent and virus-induced CASP8-mediated apoptotic signaling." (PMID 33126536, 2020). "In particular, infection with Schistosoma mansoni has demonstrated to exert a protective effect on the development of Experimental Allergic Encephalomyelitis (EAE) in infected mice reducing IFN-γ, tumor necrosis factor alpha (TNF-α) and IL-12 production and dampening the classical Th1 response." (PMID 33139781, 2020). "Although it is not well understood if NF-κB and STAT3 are activated during HTLV-1 de novo infection, we speculate that NF-κB and STAT3 are activated, as NF-κB and STAT3-regulated inflammatory molecules, including IFN-γ, IL-1, TNF-α, IL-6 and CXCL10, are produced during HTLV-1 de novo infection." (PMID 33182552, 2020). "In the following, we are exploring preventative options, which could reduce TNF alpha production without the adverse effects on infection rates and malignancy observed with anti-TNF antibody therapies." (PMID 32922301, 2020). "The ESAT-6-specific IL-17-, IFN-γ-, TNF-α-, and IL-2-producing CD4+ T-cell population in the lungs and spleen was considerably larger than that in BCG-immunised and BCG-primed ESAT-6-boosted mice, and Ag-specific CD4+CD44+ T-cells in the lungs were expanded when compared to pre-infection numbers." (PMID 32545304, 2020). "In addition, I3C treatment reduced the inflammatory response to Cr infection by maintaining anti-inflammatory cytokine IL-22 mRNA levels while reducing expression of other pro-inflammatory cytokines including IL17A, IL6, IL1β, TNF-α, and IFN-γ." (PMID 33076301, 2020). "However, despite the clear inflammatory picture associated to CBPP lesions, transcriptomic analysis of blood samples collected from CBPP affected cattle showed that genes involved in inflammation mechanisms (as TNFα) were not upregulated during the infection." (PMID 32292794, 2020). "However, the combination of simvastatin with DAPT produced a trend toward increasing levels of TNF-α and IL-1β without affecting IL-10 although these cytokines never reached the levels observed with the infection." (PMID 32393497, 2020). "In contrast to the decreased bacterial loads, the levels of the proinflammatory cytokines, TNFα (p < 0.001) and IL12 p40/70 (p < 0.05), and the percentages of iNOS+ cells were higher in planktonic bacteria-infected tissues (1 day post-infection) than those in biofilm-infected tissues." (PMID 32903626, 2020). "To determine whether fenofibrate could exert the same effect in the absence of IL-10 in the single infection model, we assessed the levels of mRNA expression of the M1 markers IL-6, TNF-α and NOS2 in knock out mice." (PMID 33072115, 2020). "When PERP knockdown followed by treatment with MY1WT in dGCs, there is an opposite trend emerged of the mRNA expression level of TNF-α (P <0.05), however, overexpression of PERP or knockdown PERP showed no significant mRNA level change of IL-6, IL-1β, TNF-α, and IFN-γ during MY1ΔsipC infection." (PMID 31565575, 2019). "Further testing by said group explored infection of macrophages with Mycobacterium ssp., Salmonella typhimurium, and Toxoplasma gondii (protozoan parasite) and demonstrated that the produced exosomes also prompted MyD88- and TLR-dependent production of TNF-α by naive macrophages." (PMID 31032233, 2019). "We hypothesize that the lack of measurable systemic TNF-α and IL-10 in blood plasma in the present experiments might be due to time delayed infection, which made it possible to mobilize the innate immune response to combat to infection." (PMID 31434337, 2019).
infection (continued). "In line with the defect of TNF-induced pS25 RIPK1 observed in IKKs or TAK1 inhibited conditions, we found that mimicking pS25 RIPK1 protected BMDMs from YopJ/P-dependent apoptosis following Y. enterocolitica (expressing YopP) and Y. pseudotuberculosis (expressing YopJ) infection." (PMID 30988283, 2019). "However, by using knock-in mice, in which only mast cells do not produce TNF, we clearly demonstrated that mast cells are not the main cell source of TNF that is required to trigger inflammation in response to infection induced by moderately severe CLP." (PMID 31212724, 2019). "In fact, elevated TNF-α concentrations could be measured in colonic ex vivo biopsies taken from mock controls at day 14 post-infection (p < 0.05 vs. naive), which was, however, not the case when mice had been challenged with mFMT (p < 0.001 vs. mock)." (PMID 31616437, 2019). "The finding that infection of hPCLS with Y. pestis lacking Pla results in increased secretion of IL-8, IL-6, and TNF-α suggests that Pla may play an early immunosuppressive role in the lung by facilitating efficient T3S of alveolar macrophages." (PMID 31085709, 2019). "In fact, subclinical infection is the result of an effective T helper 1 (Th1) cellular immunity, with the activation of macrophages by interferon-gamma (IFN-γ) and tumor necrosis factor-alpha (TNF-α) and the elimination of intracellular amastigotes via the l-arginine nitric oxide pathway." (PMID 31806038, 2019). "Analysis of CD4+ T cell subsets revealed an increase in TFH cells and IFNγ-, IFNγ+ TNF+-, and IL-2-producing CD4+ T cells and a decrease in Treg cells in Mock-immune compared with ZIKV-immune mice, which is consistent with the observation that Treg cell number peaks at day 3 after primary infection." (PMID 30677097, 2019). "However, infection of TNF−/− mice with L. major shows some delay but no defect in antigen-dependent T-cell activation." (PMID 31024534, 2019). "It is not surprising as TNF is the key mediator of the host response to infection." (PMID 31172410, 2019). "Moreover, IL-6, IL-10, TNF-α and IFN-γ mRNA were found to be significantly increased in the trigeminal ganglia (TG) of 2-week-old piglets infected with virulent PRV strain NIA3 at 2 days post-infection." (PMID 31675371, 2019). "Unfortunately, we did not measure TNF-α in this study and can therefore only speculate that in states of infection, damage or immunological danger, IL-6 leads to low levels of Hcrt1 and induces fatigue via a TNF-α-dependent mechanism." (PMID 31101054, 2019). "To assess whether similar signaling pathways operated in human monocytes encountering live S. aureus, we first determined TNFα and IFN-I production from both the human monocytic cell line THP-1 and from blood-derived CD14+ monocytes in response to infection with S. aureus." (PMID 31558608, 2019). "However, starting ssON treatment at day 3 post-infection did not lead to an increased weight in the animals and we did not detect differences in the secretion of TNF-α between the groups of animals." (PMID 31572376, 2019). "Possibly, the impact of apoptosis is more predominant after inflammation and infection to worsen the IVD degeneration, and in animal disease models, the mRNA expression of RIPK1 was lower in degeneration models after 3 months, while that of TNF was significantly higher." (PMID 31029152, 2019). "In addition, the level of TNF-α in BALF was almost the same in wild type and ΔpfbA infection." (PMID 31482074, 2019). "However, the systemic concentrations of some pro-inflammatory cytokines (IL-6 and CCL2), but not all (TNF-α, IL-1α, and IL-1β), were slightly over-induced in Ripk1LPC-KO mice at late stage of infection (72 hpi)." (PMID 30622241, 2019).